INS (insulin)
Diseases named in the same sentence as INS in open-access papers (continued):
Sharing a sentence is not in itself a finding about the gene and the disease.
diabetes (continued). "It is intended that just prior to exercise, youth living with T1D would answer questions about the exercise they are about to complete, and their diabetes management at that point in time, and would be provided with personalized insulin dose and carbohydrate advice for exercise." (PMID 39078700, 2024). "While our data highlight the importance of the fine-tuned balance of cellular redox cycles in control of ER function and insulin biosynthesis, clinical trials using antioxidants with a primary endpoint of glucose control in diabetes (hemoglobin A1c) are limited." (PMID 38935435, 2024). "In addition to pharmacological treatments, lifestyle interventions, such as regular physical activity, a balanced diet, and weight control, have been shown to improve insulin sensitivity and are essential components of managing diabetes." (PMID 39737158, 2024). "While pioglitazone use is a known risk factor for HF, the difference in the two groups as regards insulin use may also be due to the duration of diabetes being longer in the S+ group, resulting in poor beta cell reserve and need for insulin." (PMID 39606498, 2024). "Moreover, diabetes is significantly associated with uric acid stones; this can be explained by the fact that diabetics have increased insulin resistance, leading to a lower urine pH." (PMID 38595876, 2024). "In the context of diabetes treatment, insulin is known to possess additional anti-inflammatory effects, including the activation of the Nrf2 signaling pathway, which promotes the expression of antioxidant enzymes like total SOD, catalase (CAT), and glutathione peroxidase." (PMID 38550920, 2024). "Innovations in glucose monitoring and the rapid development of hybrid closed-loop insulin delivery systems have improved quality of life for patients living with diabetes, and ongoing clinical trials of novel stem-cell derived islet cell therapy have published early and highly promising results." (PMID 38476227, 2024). "One hypothesis proposed foetal insulin hypersecretion induces β-cell failure later in life resulting in diabetes." (PMID 38933924, 2024). "In diabetes, altered proportions of bacterial phyla in the intestine and consequent endotoxaemia increase the absorption of lipopolysaccharide, which spreads in circulation, initiating activation of inflammatory pathways and impairment of insulin signalling." (PMID 39062940, 2024). "Diabetes Mellitus (DM) is an endocrine disorder characterized by the body's inability to utilize glucose adequately due to insufficient levels of the hormone insulin, or due to difficulty in using the produced insulin, resulting in elevated blood glucose levels." (PMID 39476053, 2024). "Furthermore, advanced diabetes treatment technologies, such as hybrid closed-loop insulin delivery systems, were effective in enhancing patient experience with self-management and reducing diabetes-related distress." (PMID 39765957, 2024). "Regarding diabetes treatment, more than a third of the patients were on oral hypoglycemic medications (42%), and approximately 20% were on combinations of oral hypoglycemic medications and insulin." (PMID 38256553, 2024). "Taken together, our study, and the previous studies on diabetes in Zimbabwe highlight the need for policies that drive equitable access to diabetes medications such as insulin as well as screening facilities for DF, as a step toward preventing diabetes-related complications e.g., DF." (PMID 38439010, 2024). "Diabetes, through altered insulin signaling, may also impair the permeability of the blood brain barrier." (PMID 38190014, 2024). "Stem cell and regenerative therapies may ultimately manage diabetes through restored endogenous insulin production." (PMID 38720379, 2024). "In this study, insulin-loaded NPs were administered to rats with induced diabetes." (PMID 38813352, 2024).
diabetes (continued). "We hypothesized that the insulin-sensitizing adipokine adiponectin (ADP) is upregulated in cystic fibrosis related diabetes (CFRD) and underweight adults with CF." (PMID 39530118, 2024). "Furthermore, progress in materials and design methodologies plays a significant role in the creation of more compact and lighter insulin pumps, hence improving the mobility and overall quality of life for individuals managing diabetes." (PMID 39065641, 2024). "These factors comprise a younger age at which diabetes mellitus (DM) begins, the use of insulin before pregnancy in individuals with type 2 DM, lower visual clarity at the start of the study, and the existence of diabetic macular edema (DME) at the beginning of the study." (PMID 38396408, 2024). "Type 1 diabetes mellitus (T1DM) is the most common chronic autoimmune disease among children and adolescents, characterized by hyperglycemia and caused by an absolute deficiency of insulin." (PMID 38981114, 2024). "When experiencing impaired insulin-related signaling pathways, insulin resistance and hyperinsulinemia, IDE, a degrading enzyme of insulin and Aβ, is considered as a bridge linking diabetes and CI and AD via the potential signaling pathways of PI3K/AKT/GSK3β, PPARγ and NFκB." (PMID 39767690, 2024). "The study of diabetes medications revealed that dipeptidy-l peptidase 4 inhibitors were the most prescribed drugs (214 patients, 66.3%), followed by biguanides (168 patients, 52.0%), and insulin (71 patients, 22.0%)." (PMID 39107964, 2024). "Insulin is the cornerstone of treatment in type 1 diabetes mellitus." (PMID 38813352, 2024). "In the glucose-induced model of diabetes, zebrafish displayed a marked increase in blood glucose levels one hour after injection (14.3 ± 4.9 mmol/L, n = 8), while those treated with human insulin and ILP-Ap04 showed significantly lower glucose levels compared to the glucose group." (PMID 38535452, 2024). "The estimated HR for pancreatic cancer comparing 1 DDD of GLP-1RA vs 1 DDD of basal insulin, adjusted for length of diabetes, age, sex, socioeconomic status, ethnic origin, smoking, baseline BMI, and other GLM use, was 0.22 (95% CI, 0.11-0.41) for medication taken during the previous year." (PMID 38175642, 2024). "ICI-associated diabetes could be caused by the autoreactive CD8+ T-cells, which are infiltrating pancreatic islets and destroy insulin-producing beta cells." (PMID 39247185, 2024). "Current evidence showed that 18%–28.2% of patients were unwilling to start using insulin, 38%–44.8% of patients believed that insulin interfered with and restricted their daily lives, and 38%–78% of patients believed that insulin was the last way to treat diabetes." (PMID 39036047, 2024). "Today, for people with type 1 diabetes and, maybe, some people with type 2 diabetes, insulin therapy is the cornerstone of diabetes care." (PMID 38645750, 2024). "In this population-based nationwide study, we showed, that PWD were significantly more likely to participate in DSME if they had a medium or high level of education, had type 1 diabetes, were receiving insulin treatment, and had diabetes for more than five years." (PMID 39264968, 2024). "A meta-analysis demonstrated that combining aerobic exercise and dietary therapy had a significant positive impact on diabetes, improving blood glucose, insulin, and HbA1c, along with BMI, waist circumference, blood pressure, total cholesterol, and triglycerides." (PMID 38612998, 2024). "In this study, diabetes induction by alloxan resulted in considerable (P<0.05) suppression of Pdx-1 expression and DNA binding capabilities, which subsequently impaired the expression of insulin genes (Ins-1 and Ins-2)." (PMID 38234664, 2024).
diabetes (continued). "More specifically, disorders of glucose metabolism, ranging from clinically silent insulin resistance through degrees of hyperglycemia defining prediabetes and diabetes, can precipitate changes in the lung consistent with asthma through pathways principally involving insulin excess." (PMID 38398039, 2024). "Given our concern regarding the role of TRPV1 in insulin secretion, as well as its potential involvement in diabetes-related vascular lesions and neuropathy, we posit that TRPV1 represents a promising avenue for future research into the pathogenesis and treatment of diabetes." (PMID 38255767, 2024). "The oxidation of low-density lipoprotein cholesterol is exacerbated by copper, causing atherosclerosis and increasing the risk of cardiovascular disease.In addition, high serum copper concentrations lead to insulin resistance and abnormal insulin secretion, which promotes diabetes." (PMID 38707892, 2024). "In particular, the risk of developing diabetes increases in middle- and old-aged people because of increased insulin resistance, aging, and lack of physical activity." (PMID 39594155, 2024). "Exploring diabetes monitoring through polyphenol supplementation should be expanded, particularly given the promising results observed in other preclinical studies regarding the insulin-sensitising properties of polyphenols." (PMID 38700145, 2024). "BCAAs have been widely reported to be involved in the pathogenesis of diabetes, which might impair insulin signaling and lead to increased insulin secretion and pancreatic β-cell exhaustion." (PMID 39302270, 2024). "Diabetes mellitus (DM), per se, is a chronic metabolic disorder characterized by persistent hyperglycemia, primarily resulting from impaired insulin secretion, resistance to insulin’s peripheral actions, or a combination of both." (PMID 38775536, 2024). "These include gender, duration of diabetes, age at diabetes diagnosis, poor glycaemic control, diabetes-related microvascular complications (neuropathy, nephropathy, retinopathy), insulin therapy, body mass index, smoking, lipid abnormalities and prior amputation." (PMID 39650092, 2024). "Contemporary medical research reveals that the pathogenesis of diabetes involves complex interactions including insulin resistance, defects in insulin secretion, viral infections, inflammatory responses, and gastrointestinal effects, significantly influencing its development and progression." (PMID 39777222, 2024). "I take my diabetes medication (e.g. insulin, tablets) as prescribed/agreed." (PMID 39044279, 2024). "It was speculated that the beneficial effect of CDAI on hyperlipidemia may have been weakened in diabetic mellitus patients due to the control of a diabetic diet as well as the administration of insulin and hypoglycemic drugs." (PMID 38987566, 2024). "Two significant examples that reinforce the role of INS as a social substance and the need for integrative interventions, including those in the psychosocial realm, are Type 2 Diabetes Mellitus (T2DM) with musculoskeletal disorders (MSDs) and T2DM with neurodegeneration." (PMID 39595105, 2024). "Adherence to insulin therapy is crucial to managing diabetes effectively." (PMID 38542928, 2024). "However, in patients with diabetes, insulin function is impaired and cells become less responsive to glucose, leading to high blood sugar levels." (PMID 39433858, 2024). "Considering the fact that insulin is naturally produced in pancreatic beta cells and oxidative stress occurs in Diabetes that may affect insulin, we further investigated the effects of oxidized insulin on INS1E cells." (PMID 39378614, 2024). "Similarly, adjustment of anti-diabetic medications, insulin type and dosing greatly impact incidence of adverse events during Ramadan in people living with diabetes." (PMID 38827884, 2024).
diabetes (continued). "In Japanese patients with both severe obesity and T2D, circulating levels of the diabetes-associated hepatokines, SeP, did not alter during the course of weight reduction, possibly biased by a reduction in glucose and insulin and metformin washout." (PMID 37957316, 2024). "Studies should assess whether current diabetes treatments, such as medications and insulin pumps, can improve sleep architecture." (PMID 39597994, 2024). "Despite not having a diagnostic code for diabetes, 12% of patients classified as not having diabetes had received prescriptions for insulin." (PMID 38911638, 2024). "The use of insulin lies at the heart of diabetes treatment, and its role cannot be ignored." (PMID 39190215, 2024). "Insulin, functioning as a growth hormone by binding to the insulin-like growth factor receptor (IGF-R), has been linked to a more aggressive course of cancer in patients with type 2 diabetes mellitus (T2DM), as indicated by prior studies." (PMID 38672620, 2024). "Both parents and children in the study were motivated by the prospect of accessing the latest technology, specifically an insulin pump and continuous blood glucose monitoring device, which were offered to both the intervention and control groups within one week after diabetes diagnosis." (PMID 39360673, 2024). "For DKD, both LASSO and GBDT selected 5 risk factors (duration of diabetes, history of CVD, antihypertensive medication use, age, and insulin use) and 4 metabolites (tyrosine, lactate, cholesterol esters to total lipid ratio in intermediate-density lipoprotein particles [IDL-CE%], and citrate)." (PMID 38546730, 2024). "For such people, according to our data, a practice diabetes nurse could have been highly beneficial by facilitating an earlier initiation of insulin treatment and thus attainment of better glycemic control." (PMID 38116986, 2024). "Third, because the NHANES variable database is huge, it is impossible to include all the covariates related to diabetes, such as insulin resistance, blood glucose control, and follow-up, so the results may be affected by the loss of some important variables." (PMID 39188897, 2024). "Diabetes is classified into two types: Type 1, an autoimmune disorder in which the pancreas produces little or no insulin, and Type 2, which is characterized by insulin resistance and/or impaired insulin secretion." (PMID 39610875, 2024). "Additionally, a longer duration of diabetes, younger age at onset, and the utilization of insulin have been identified as robust predictors of DR." (PMID 38646317, 2024). "Post-pregnancy, β cells, blood glucose levels, and insulin sensitivity may normalize or may sustain impairment, potentially leading to gestational diabetes mellitus in future pregnancies or type 2 diabetes mellitus." (PMID 39597780, 2024). "However, when type 1 diabetes mellitus (T1DM) patients (with low insulin production) were provided a subcutaneous GIP infusion, they showed an increase in NEFA levels during the first 3 h, without changes in fasting plasma levels of C-peptide or insulin." (PMID 38579777, 2024). "Hence, the strategies and processes that would involve diabetes educators to execute the pre-visit insulin PDA use, and referral of patients to diabetes educators for detail use of the insulin PDA would not be feasible." (PMID 39546450, 2024). "What is the best choice of insulin type in the management of diabetes?" (PMID 38997722, 2024). "It plays a regulatory role in insulin secretion and diabetes mellitus." (PMID 39659616, 2024). "Moreover, the onset of diabetes occurs earlier in females, with a median incidence at 18 weeks, although a marked decrease in insulin content is already observed at 12 weeks of age20." (PMID 38918575, 2024).
diabetes (continued). "No miRNAs were deregulated in AGE and in the same direction in ACC, but the uniquely rejuvenated miRNAs were enriched in certain pathways in MAT (‘insulin resistance’, ‘adipocytokine pathway’, ‘type 2 diabetes mellitus’), which again have a role in nutrient sensing." (PMID 37106037, 2024). "Improving insulin resistance by lowering glucose levels via non-insulin dependent pathways, such as exercise, is a crucial component of targeting the alarming increase in diabetes rates, as well as improving risk in non-diabetic individuals." (PMID 38572086, 2024). "Intensive insulin therapy for patients undergoing cardiac surgery with diabetes or perioperative hyperglycemia resulted in a 48% reduction in mortality and a 24% decrease in POAF incidence, suggesting that insulin may reduce susceptibility to POAF." (PMID 39541171, 2024). "Research indicates that the BDNF Val66Met polymorphism may modulate cardiometabolic markers, such as the dietary insulin index and dietary insulin load, particularly in individuals with diabetes." (PMID 38988887, 2024). "A study in China (N = 3100) reported that, after adjusting for age, sex, duration of diabetes, BMI, HbA1c, BP, and albuminuria creatinine ratio and insulin treatment, age at diagnosis and postprandial C-peptide (OR, 0.92; 95% CI, 0.86–0.94) were independently associated with DR." (PMID 38694495, 2024). "The effect of insulin on diabetic HTG was assessed on Day 60 post‐diabetes induction." (PMID 39529532, 2024). "Additionally, these compounds enhance insulin sensitivity, which aids in more effective glucose uptake into cells, a vital aspect of diabetes care." (PMID 38921380, 2024). "Achieving financial independence is a core developmental task for this age group, but for those with type 1 diabetes (T1D), the high costs of insulin and diabetes supplies as well as an employment-based insurance model with minimal safety net can make this a formidable challenge." (PMID 38344219, 2024). "Therefore, we recommend that patients with COPD who also have diabetes, high BP, dyslipidemia, or reduced fasting glucose levels begin using insulin, lipid-lowering medications, and oral hypoglycemic medications." (PMID 38800162, 2024). "Diabetes mellitus is a chronic endocrine disorder that affects insulin secretion and action." (PMID 38523307, 2024). "Loci for the other genes—PTP4A1, APOBR, BMS1P4-AGAP5, MAPK8IP1P1, GYS2, FAM25C, and GK5–were formerly associated with traits involved with comorbidities of OSA, i.e., BMI, weight, triglycerides, blood pressure, stroke, brain volume, cortical thickness, mood, insulin, and diabetes." (PMID 39457448, 2024). "The pathogenesis of diabetes involves insulin resistance in tissues (such as adipose tissue, muscle, and liver) and insufficient insulin secretion in pancreatic cells, which may lead to hyperglycemia." (PMID 37795833, 2024). "The organoids were found to acquire glucose-stimulated insulin secretion within 10 days and to restore glucose homeostasis in diabetic mice within 100 days post-transplantation, providing a potentially promising new approach to diabetes treatment." (PMID 39281285, 2024). "A research study highlighted the favorable outcomes of Iranian propolis supplementation for individuals with type 2 diabetes mellitus, showing declines in postprandial blood glucose, serum insulin, insulin resistance, and inflammatory cytokines while also indicating elevations in HDL levels." (PMID 38474354, 2024). "Telemedicine and remote communication with diabetes care providers enabled adolescents and their parents/guardians to receive guidance about insulin dosing decisions, lifestyle changes, and other strategies to manage their condition more efficiently while at home." (PMID 39867016, 2024).